P2RX3 (purinergic receptor P2X 3)
Description:
Extracellular ATP-activated non-selective cation channel. Plays particularly important role in sensory neurons where its activation is critical for gustatory, nociceptive responses, visceral reflexes and sensory hypersensitization (By similarity).
Synonyms: P2X3
Tractability: Small molecule: a drug acting on it is in phase 2 or 3 trials; a structure with a bound ligand is known; a high-quality ligand is known; it belongs to a druggable protein family. Antibody: UniProt places it where antibodies can reach, with high confidence; its Gene Ontology location is reachable by antibodies, with high confidence; UniProt predicts a signal peptide or a membrane-spanning region. PROTAC: ubiquitination databases record sites on it; a small molecule that binds it is known.
Target class: Ligand-gated ion channel; P2X receptor; Ion channel
Chemical probes: CHEMBL3091630, Sivopixant
Safety:
Unwanted effects reported when the protein is acted on. In parentheses: how it was acted on, where the effect was seen, and who reports it.
decreased convulsions (inhibition, acute dosing; nervous system, renal, immune; source: Lynch et al. (2017))
decreased inflammation (inhibition, acute dosing; nervous system, renal, immune; source: Lynch et al. (2017))
decreased pain (inhibition, acute dosing; nervous system, renal, immune; source: Lynch et al. (2017))
hemolysis (activation, acute dosing; nervous system, renal, immune; source: Lynch et al. (2017))
increased pain (activation, acute dosing; nervous system, renal, immune; source: Lynch et al. (2017))
increased urinary sodium excretion (activation, acute dosing; nervous system, renal, immune; source: Lynch et al. (2017))
increased urine excretion (activation, acute dosing; nervous system, renal, immune; source: Lynch et al. (2017))
neurodegeneration (activation, chronic dosing; nervous system, renal, immune; source: Lynch et al. (2017))
Gene: Protein-coding gene on chromosome 11 (57,338,352 to 57,372,404, forward strand). Ensembl gene ENSG00000109991.
Subcellular location: Cell membrane
Pathways (Reactome):
Hemostasis: Elevation of cytosolic Ca2+ levels; Platelet homeostasis
Gene Ontology:
Molecular function: ATP binding; extracellularly ATP-gated monoatomic cation channel activity; purinergic nucleotide receptor activity; monoatomic ion channel activity
Biological process: calcium ion transmembrane transport; cellular response to ATP; protein homotrimerization; transmembrane transport; positive regulation of calcium ion transport into cytosol; positive regulation of calcium-mediated signaling; signal transduction; excitatory postsynaptic potential; modulation of chemical synaptic transmission; monoatomic cation transmembrane transport; monoatomic ion transport; purinergic nucleotide receptor signaling pathway; response to ATP
Cellular component: plasma membrane; receptor complex; axon; hippocampal mossy fiber to CA3 synapse; membrane; neuron projection; postsynapse; Schaffer collateral - CA1 synapse
Genetic constraint (gnomAD): Loss-of-function variants: 39 observed, 48.95 expected, observed/expected ratio (o/e) 0.8, 90% interval 0.62 to 1.04. The upper end of that interval is the gene's LOEUF score, 1.04, which puts it in group 4 of 6, group 1 being the genes least tolerant of losing a copy. Missense variants: 455 observed, 521.74 expected, observed/expected ratio (o/e) 0.87, 90% interval 0.81 to 0.94. Synonymous variants: 184 observed, 190.21 expected, observed/expected ratio (o/e) 0.97, 90% interval 0.86 to 1.09.
Homologues: Orthologues: chimpanzee P2RX3 (99% identical), pig P2RX3 (95% identical), rat P2rx3 (94% identical), mouse P2rx3 (94% identical), guinea pig P2RX3 (90% identical), rabbit P2RX3 (89% identical), dog P2RX3 (88% identical), macaque P2RX3 (84% identical), zebrafish p2rx3b (68% identical), zebrafish p2rx3a (57% identical). Paralogues in human: P2RX2 (48% identical), P2RX4 (43% identical), P2RX1 (42% identical), P2RX5 (42% identical), P2RX6 (38% identical), P2RX7 (38% identical).
Diseases named in the same sentence as P2RX3 in open-access papers:
P2RX3 is named in the same sentence as 68 diseases in open-access papers, as found by Europe PMC text mining. Sharing a sentence is not in itself a finding about the gene and the disease. The quoted sentences say what the papers report.
endometriosis (7 papers, 2014 to 2025). The growth of functional endometrial tissue in anatomic sites outside the uterine body. "We believe this is the first study to detect differences in the expression of mRNAs encoded by the ion channels TRPA1, P2RX3, SCN9A, and SCN11A in the peritoneum and lesions of women suffering from CPP, some of whom had endometriosis." (PMID 25029427, 2014). "In summary, the results of this study indicate that therapies targeting P2RX3 may be useful in treating CPP in women with a diverse range of painful etiologies, whereas women with active endometriosis could benefit from treatments targeting TRPV1, TRPA1, SCN9A, or SCN11A." (PMID 25029427, 2014). "P2RX3 mRNA was increased in the peritoneum of women with CPP, with and without endometriosis (P < .05)." (PMID 25029427, 2014). "Notably, P2RX3 mRNAs were significantly elevated in the peritoneum of women with CPP, regardless of whether they had active endometriosis and would be consistent with a neuropathic component to idiopathic CPP." (PMID 25029427, 2014).
migraine (6 papers, 2013 to 2023). "The neuropeptide CGRP is considered to play a key role in the pathophysiology of migraine and was shown to cause a delayed increase in P2rx3 mRNA in cultured mouse trigeminal neurons." (PMID 27213950, 2016).
Cough (3 papers, 2021 to 2023). A sudden, audible expulsion of air from the lungs through a partially closed glottis, preceded by inhalation. "Consistently, P2rX3−/− mice developed significantly less number of coughs than their WT littermates in the rodent cough model." (PMID 37730705, 2023).
Headache (3 papers, 2006 to 2016). Cephalgia, or pain sensed in various parts of the head, not confined to the area of distribution of any nerve. "Moreover, transcriptional alteration in individual genes like the pain receptor P2rx3 and the circadian clock gene Per1 are interesting findings in relation to NO-provoked headache." (PMID 27213950, 2016).
type 2 diabetes mellitus (3 papers, 2020 to 2024). A type of diabetes mellitus that is characterized by insulin resistance or desensitization and increased blood glucose levels. "The results show that the HTWP-acupuncture alleviation of the TBI-induced coma duration was offset by the i.c.v injection of P2RX7, P2RX3, and TRPV1 antagonists, indicating that P2RX7, P2RX3, and TRPV1 signaling pathways mediate the awakening effect of acupuncture at HTWP." (PMID 33519382, 2020). "Thus, we analyzed the distribution of P2RX7, P2RX3, and TRPV1 in the vPAG of sham and TBI rats without or with HTWP acupuncture treatment using confocal microscopy to verify that HTWP acupuncture regulates the expression of these receptors in the vPAG to reduce coma duration." (PMID 33519382, 2020).
pulmonary disease (2 papers, 2020 to 2021). "For example, CLP1 is linked to cardiac muscle hypertrophy, YPEL4 has a role in pulmonary diseases, P2RX3 and ENSGALG00000007381 are involved in blood coagulation (Reactome; Uniprot), and SLC43A3 plays a possible important role in the repair and growth of the lung tissue under oxidative stress." (PMID 34021753, 2021).
alcohol (1 paper, 2016). "Our result suggests ethanol-induced dysregulation of P2RX3 along with alterations in molecules involved in neural activity such as neuroactive ligand-receptor interaction may be a molecular event associated with alcohol-related peripheral neuropathy of an enhanced nociceptive response." (PMID 27682028, 2016).
Hearing impairment (1 paper, 2020). A decreased magnitude of the sensory perception of sound. "Interestingly, one of the closely related family members of P2rx3, P2rx2, has been implicated in hearing loss associated with DFNA41." (PMID 32675174, 2020). "Whether loss of P2rx3 leads to hearing impairment remains an open question." (PMID 32675174, 2020).
inflammatory skin disease (1 paper, 2025). Inflammatory skin disorders covers a broad category that includes many conditions ranging in severity, from mild itching to grave medical health complications These disorders are common in people of all ages and races. "Single-cell transcriptomic analyses of dorsal root ganglia have identified pruriceptive neuron subsets co-expressing P2rx3 and itch-related markers, supporting P2X3 as a molecular signature in sensory neurons involved in inflammatory skin diseases." (PMID 41235218, 2025).
viral infection (1 paper, 2021). "ACE2 expression in the human dorsal root ganglion (DRG) sensory neurons and in P2RX3 (purinergic receptor P2X3) pain receptors and the subsequent damage of these nerves upon viral infection might be responsible for the post-COVID neurological symptoms." (PMID 34393976, 2021).
tumor (9 papers, 2014 to 2025). "P2RX3, has been reported to be involved in tumour formation and play an important role in malignant transformation of several different cell types and they are highly expressed in cancer." (PMID 37875584, 2023). "Studies from our group and others have demonstrated that tumor cells upregulate the P2 purinergic receptors P2RY1, P2RY2, P2RX3 and P2RX7 and utilize extracellular ATP to support tumor growth and metastasis." (PMID 33420030, 2021).
P2RX3 also shares sentences with these, for which no sentence is quoted: cancer (9 papers); bone cancer (5); neuropathic pain (5); diabetes (4); colitis (3); Hypertension (3); ischemia (3); overactive bladder (3); peripheral nerve injury (3); asthma (2); Bladder (2); Hyperglycemia (2); infection (2); inflammatory bowel disease (2); interstitial cystitis (2); peripheral neuropathy (2); astrocytoma (1); breast carcinoma (1); cardiovascular disease (1); chronic kidney disease (1); chronic pancreatitis (1); Cluster headache (1); Coma (1); diabetic neuropathies (1); dry mouth (1); Dysmenorrhea (1); fibrosarcoma (1); gastric cancer (1); gastroesophageal reflux disease (1); glaucoma (1).
A further 27 diseases each share a sentence with P2RX3 in 1 paper.